NRAS (NRAS proto-oncogene, GTPase)
Diseases named in the same sentence as NRAS in open-access papers (continued):
Sharing a sentence is not in itself a finding about the gene and the disease.
melanoma (continued). "Using BRAF and NRAS mutation analysis, it could be proven that both lesions were melanoma metastases instead of SFT." (PMID 25593912, 2014). "BRAF and NRAS genes typically show a mutually exclusive mutation pattern in melanoma samples." (PMID 24516372, 2014). "NRAS mutations were also detected in 38/177 (22%) melanoma samples using the MALDI-TOF panel." (PMID 24956168, 2014). "Mutations in the NRAS gene have also been observed in approximately 15-20% of melanomas." (PMID 25074438, 2014). "Notably, the majority of these truncation mutations co-occur with BRAF and NRAS mutations, suggesting a potential cooperating role during the progression of melanoma." (PMID 25393105, 2014). "In addition, inhibition of MEK (the only known phosphorylation substrate of BRAF) is considered to be a valid therapeutic intervention for both BRAF- and NRAS-mutated melanoma." (PMID 24743024, 2014). "Activated alleles of the NRAS gene are the second most common oncogenic mutations in melanoma." (PMID 24550252, 2014). "Finally, sequence analysis of the exon 4 and 5 of GNAQ gene, whose mutations have been associated with wild type BRAF and NRAS melanomas, revealed wild type status in all samples." (PMID 24238212, 2013). "Overall 65% of melanoma had a BRAF or NRAS mutation in a mutually exclusive pattern." (PMID 23694694, 2013). "Notably, BRAF and NRAS mutations are mutually exclusive in melanoma, which is also observed in our study." (PMID 24023633, 2013). "In the remaining discrepant cases, we surprisingly observed a mutated primary tumor and a wild-type metastasis (93% BRAF and 7% NRAS) or, to a less extent, a different mutation pattern between melanoma lesions (NRAS mutation in primary and BRAF mutation in secondary tumors)." (PMID 23987572, 2013). "It is not known whether melanocytic nevi that are found in association with a melanoma are more likely to carry BRAF or NRAS mutations than uninvolved nevi." (PMID 23861977, 2013). "In vitro, melanoma cells with NRAS mutations are dependent on NRAS for survival and proliferation." (PMID 27429256, 2013). "We found that both the BRAF-mutated 1205Lu and NRAS-mutated WM1366 melanoma cell lines retain their sensitivity to dinaciclib when grown as 3D collagen-implanted spheroids, suggesting that modulating the tumor microenvironmental conditions does not increase resistance to this compound." (PMID 23527225, 2013). "The outstanding importance of the RAS/RAF signaling pathway is documented by the observation that BRAF and NRAS mutations—exclusively NRAS or BRAF is mutated in a tumor—together are found in over 80% of melanomas and by inhibitors of mutated BRAF that are clearly effective in melanoma therapy." (PMID 23634303, 2013). "We also found that all of the NRAS mutated melanoma lines evaluated (or included in our panel) had low expression of CDK2, whereas there was some variability within the BRAF-V600E mutated group, with some cell lines harboring high expression of CDK2 and some with low expression." (PMID 23527225, 2013). "Hence, in melanomas in which BRAF or NRAS mutations are present, they would be expected to be responsive to therapeutic interventions targeting the RAS-RAF-ERK and PI3K pathways, such as sorafenib." (PMID 22110486, 2012). "In addition to BRAF inhibitors, patients are directed to trials for KIT mutations, GNAQ/11 mutations in uveal melanoma, and even NRAS mutant melanoma." (PMID 22536370, 2012). "However, evidence for constitutive phosphor-JNK expression was also found in human melanoma lines expressing BRAF or NRAS activating mutations." (PMID 23173060, 2012). "Interestingly, combined BRAF (GSK2118436) and MEK (GSK1120212) inhibition was recently shown to overcome NRAS-mediated resistance to BRAF inhibition in melanoma cells already harbouring BRAFV600 mutations." (PMID 23039341, 2012). "NRAS mutations are present in 15-30% of melanomas, but are rarely coincident with BRAF mutations." (PMID 21505228, 2011).
melanoma (continued). "While it is clear that CRAF activation and enhanced MAPK pathway signaling occur in BRAFWT melanoma cells (particularly those which harbor an NRAS mutation) treated with BRAF inhibitors such as vemurafenib and PLX4720, the clinical relevance of this is uncertain." (PMID 22175026, 2011). "NRAS mutations found in the melanoma samples using a combination of DNA sequencing and ARMS." (PMID 20925915, 2010). "Therefore, dependency of growth response on NRAS mutation after treatment with PLX4032 should be further explored once growth factor-dependent BRAFWT/NRASWT melanoma cells become available." (PMID 20149136, 2010). "Early clinical studies revealed evidence of Hsp90 target modulation and some signs of biological activity (stable disease) in melanoma patients that may potentially be associated with the presence of BRAF or NRAS mutation." (PMID 21037799, 2010). "HCT116, a colon cancer line that harbors a KRASG13D mutation and IPC298, a cutaneous melanoma cell line bearing an NRASQ61L mutation, were chosen for this study since KRAS in colorectal cancer and NRAS in melanoma is the most frequently mutated RAS gene in these tumor types." (PMID 19492075, 2009). "Notably, BRAF, a downstream activator in the RAS pathway is mutated in nearly 70% of human melanoma (BRAFV600E activating mutation) while NRAS activating mutations occurs in 30% of melanomas (NRASQ61L activating mutation)." (PMID 19274086, 2009). "KIT mutations are mutually exclusive with BRAF and NRAS, and may identify a subset of melanoma that preferentially respond to the KIT inhibitors such as imatinib (Gleevec) or sorafenib." (PMID 19949544, 2009). "This is contrary to our initial hypothesis about BRAF playing a dominant role in tumor cell signaling in melanomas bearing an NRAS mutation." (PMID 19492075, 2009). "Interestingly, BRAF mutations are mutually exclusive with NRAS mutations in melanoma and KRAS mutations in colorectal cancer." (PMID 19492075, 2009). "In addition, NRAS‐mutant melanoma could be compared with other mutated melanomas to better understand the nature of this cancer and the characteristics conferred by different mutations." (PMID 41486569, 2026). "In addition, we found that NRAS-mutated melanomas were significantly associated with AHM subtype." (PMID 40867317, 2025). "While NRAS Q61 activating mutations are common drivers of adult and paediatric melanoma, this specific residue substitution (Q61H) has recently been characterised as the least aggressive in driving melanoma development, compared to other Q61 missense mutations." (PMID 41168392, 2025). "Evaluation of FNTB levels as well as NRAS mutation status could provide potentially treatment-predictive information that could guide the design of future clinical trials including tipifarnib or other FTIs in melanoma." (PMID 39995872, 2025). "Moreover, recent evidence suggests that the pirin-MRTF axis may be influenced by upstream oncogenic signalling events, particularly those associated with BRAF or NRAS mutations, prevalent in melanoma." (PMID 40740997, 2025). "Thus, its antiproliferative effect in melanoma cells presenting NRAS mutation is unprecedented, and, moreover, it may be of great therapeutic relevance." (PMID 40141318, 2025). "In addition, in two different xenograft mouse models harboring tumors from NRAS mutated patient‐derived melanoma cells combination therapy showed superior anti‐tumor effects compared to animals administered either monotherapy, resulting in significant survival advantages." (PMID 41199020, 2025). "However, the relationship between ACKR2 expression and BRAF/NRAS mutations in melanoma remains unclear and warrants further investigation." (PMID 40248897, 2025). "However, both AMPK activators synergistically potentiated RocA-induced ERK-dependent luciferase production in NRAS-mutated MelJuso melanoma cells, where the maximal luciferase activity was approximately 300-fold higher than the activity observed in untreated controls." (PMID 39436655, 2024).
melanoma (continued). "Notably, melanoma exhibits a relatively high frequency of NRAS mutations." (PMID 38982514, 2024). "Moreover, ddPCR was able to detect low-frequency hotspot mutations, such as NRAS G12/G13, in our tissue specimens, which makes it a promising tool for investigating the mutational landscape of sun-damaged skin, benign nevi, and melanomas in more extensive clinical studies." (PMID 38396984, 2024). "However, the efficacy of immunotherapies for treating melanomas with NRAS mutations is contentious." (PMID 38462618, 2024). "Here, we investigated whether particular long non-coding RNAs (lncRNAs) may be specifically associated with the tumorigenicity of NRAS-mutated/MAPK-driven melanoma, and whether such lncRNAs may be amenable for therapy using cutting-edge RNA-targeting interventions (ASO)." (PMID 38383439, 2024). "Additionally, NRAS mutations are better prognosis indicators in melanoma patients received ICIs19." (PMID 39025927, 2024). "However, we were able to detect low-frequency hotspot mutations, such as NRAS G12/G13, in our healthy skin, nevi, and melanoma sample specimens, suggesting that, due to its increased sensitivity, ddPCR technology can provide new and relevant information for future studies in the field." (PMID 38396984, 2024). "Moreover, the SP‐01 tumor presents an activating mutation in the ERBB4 gene, which is described as a driver of BRAF wild‐type (WT) melanomas, and SP‐06 presents an oncogenic NRAS mutation, inactivation of NF2, and a truncating mutation in SMARCA4 (in one allele)." (PMID 37798904, 2024). "Therefore, we tested our hypothesis of using miR-708 to inhibit NRAS mutation-driven cancer in three types of cancer cell lines: melanoma, AML, and NSCLC." (PMID 37083947, 2023). "Furthermore, outcomes for melanoma with NRAS and KIT mutation receiving adjuvant immunotherapy remain unclear." (PMID 37403699, 2023). "Moreover, NRAS mutations occur in approximately 20% of malignant melanomas." (PMID 38111008, 2023). "However, BRAF/NRAS-activating mutations are less frequently mutated in MM compared to CM: 6% and 8%, respectively, versus 50% and 28% in CM, with a variable incidence depending on the anatomical district of melanoma occurrence." (PMID 37773078, 2023). "Therefore, combined treatment with EZH2 and MEK1/2 inhibitors may provide a novel promising therapeutic strategy for NRAS-mutated and wild-type melanomas, as these types of melanomas are resistant to BRAF inhibitors." (PMID 37325482, 2023). "However, its role in BRAF as compared to NRAS mutated melanoma needs further investigation." (PMID 36982192, 2023). "However, we did not investigate whether a single Nras61R allele has the potential to drive spontaneous melanoma formation or if wild-type NRAS can prevent tumor initiation by melanomagenic mutants other than NRAS61R." (PMID 35672316, 2022). "Additionally, the potential therapeutic value of MEK inhibitors combined with inhibition of downstream effectors (MAPK, PI3K, or CDK4/6) or upstream effectors (RTK, STK19) for melanomas with NRAS mutations has been demonstrated, but the choice remains controversial." (PMID 36125617, 2022). "In addition, this study revealed an increase in Adenosine-to-Inosine editing in Alu regions and in non-repetitive regions, including the hyperediting of the MOK and DZIP3 genes in relapsed tumour samples during targeted therapy and of the ZBTB11 gene in NRAS mutated melanoma cells." (PMID 35993275, 2022). "However, it persists vague whether various NRAS mutations produce distinctive biological or clinical characteristics in melanoma." (PMID 36551688, 2022). "However, the results from the POLARIS-01 study showed that NRAS mutation may be a potential resistance mechanism of immunotherapy in advanced melanoma patients." (PMID 35967450, 2022). "Notably, NRAS mutations are associated with nodular subtypes of melanoma and with poorer outcomes." (PMID 35712493, 2022).
melanoma (continued). "At variance, in vitro studies with ERβ agonists have suggested that they could inhibit the proliferation of melanoma cells harboring the NRAS mutation, an important gene of the RAS family, indicating that ERβ might impair melanoma onset through inhibition of the PI3K/Akt pathway." (PMID 34209162, 2021). "Additionally, NRAS mutations have been found in 15–20% of melanoma cases." (PMID 33807778, 2021). "There are a number of less penetrant mutations associated with melanoma proliferation: NRAS mutation is the next most common cause of aberrant signaling within the MAPK pathway and may be responsible for as many as 30% of somatic mutations affecting the MAPK cascade." (PMID 34155457, 2021). "Our results support the notion that further activation of MAPK signaling through loss of inhibitors such as DUSP4 in melanoma cells that already harbor activating BRAF or NRAS mutations is detrimental, a hypothesis that will need to be explored with further experiments." (PMID 32767816, 2021). "Interestingly, 20–30% of NF1 deletions have been found in BRAF and NRAS wild type melanomas suggesting that NF1 may be implicated in MAPK pathway activation." (PMID 34680938, 2021). "However, the clinical correlates of BRAF and NRAS mutations in melanoma BM are limited." (PMID 33578810, 2021). "In some cases, Met activation could be associated with NRAS mutation in melanoma." (PMID 33918490, 2021). "Additionally, G9a targeted therapies may help a wider range of melanomas, since the amplification of G9a occurs in the context of both BRAF- and NRAS-activating mutations, which are the two most common oncogenic drivers of melanoma." (PMID 34691767, 2021). "Our data demonstrate that PPP2R3B overexpression promotes proliferation of NRAS-mutant melanoma cell lines, which could explain the predisposition to the development of a clinically apparent melanocytic nevus or melanoma in the context of a somatic pathogenic variant in a melanocyte." (PMID 34145395, 2021). "Interestingly, genomic analysis of MUPs has found they have a mutational profile more similar to cutaneous melanoma than that of mucosal melanoma or CNS melanoma, including mutations in BRAF and NRAS, suggesting that regression or misdiagnosis of a previous cutaneous lesion was the primary melanoma." (PMID 32652526, 2020). "Notably, NRAS-mutated melanomas in our study were related to lower CD2 expression levels." (PMID 33003444, 2020). "Therefore, BRAF or NRAS-mutated melanomas represent the vast majority of patients." (PMID 32664549, 2020). "While mutations of BRAF and NRAS are the most commonly described in melanoma cells, a number of less common aberrations have been identified, which might also provide new therapeutic opportunities and identification of new targets continue to increase therapeutic options." (PMID 32575838, 2020). "Moreover, NF1 together with BRAF and NRAS has been found significatively mutated in melanoma." (PMID 32850962, 2020). "However, it has to be considered that the BRAF/NRAS mutation frequency is very low in mucosal melanoma, therefore the KIT mutation rate must be much higher in mucosal melanoma as compared to cutaneous locations but a statistical analysis cannot be done on our small cohort." (PMID 31848942, 2020). "Therefore we wondered whether 17-AAG could inhibit the PLX4032-induced ERK activation in NRAS mutated human melanoma cells." (PMID 29481571, 2018). "Indeed, NRAS mutations in melanoma are associated with a reduced presence of tumor‐infiltrating immune cells, suggesting an immunosuppressive microenvironment, which might explain the poor response to immunotherapy." (PMID 29661909, 2018). "Moreover, our proof-of-principle study focused on the driver mutations BRAF and NRAS, which account for up to 70% of melanomas, and are well suited to this purpose because of the low likelihood of clonal diversity with trunk mutations such as these in melanoma." (PMID 29112704, 2018).
melanoma (continued). "Thus, Usp9x-mediated regulation of NRAS expression in melanoma, particulalrly in NRAS mutant cells, may partly underly their dependence on Usp9x for continual expansion and survival." (PMID 28198367, 2017). "Importantly, NF1 mutations have been found in melanomas that lack both BRAF and NRAS mutations, with 25–30% of such melanomas found to harbour deleterious NF1 mutations, thus implying that NF1 inactivation has conferred aberrant MAPK pathway activation in these tumours." (PMID 28637487, 2017). "Also, the higher NRAS mutation rates in the South Island suggest that South Island melanoma patients could benefit more often from the use of immune checkpoint blockade therapy, which has higher response rates in NRAS mutant melanomas." (PMID 27191502, 2016). "In addition to mutated BRAF, mutated NRAS accounts for about 20% of melanoma cases." (PMID 27941674, 2016). "However, they also indicated a role for β-catenin in the stimulation of melanoma metastatic potential when combined with activating mutations in NRAS, indicating that the role of Wnt signaling may be context dependent." (PMID 25915038, 2015). "However, it is clear that BRAF WT cells also respond to iHsp90s with increased antigen expression, as cells expressing only NRAS mutations, as well as cells that are WT for both of these genes, (such as the human gliomas) and the murine melanoma) all are susceptible to iHsp90 antigen induction." (PMID 25503774, 2014). "Therefore it is unknown if BRAF or NRAS mutations play any role in the progression of a nevus into a melanoma." (PMID 23861977, 2013). "PLX4032 enhanced the rate of proliferation of mitogen-dependent primary melanoma cells carrying the NRAS Q61L mutation, and decreased adhesion and increased migration, of rapidly dividing melanoma cells from advanced lesions, changes that may confer tumor advantage in vivo." (PMID 20149136, 2010). "This is possibly because NRAS-mutated melanoma may bypass BRAF and signal through CRAF." (PMID 19949544, 2009). "Our study describes a novel ERK5/KLF4/AXL signaling axis that drives MEKi resistance and metastatic potential in NRAS-mutant melanoma and highlights this axis as a potential target to improve MAPK-directed and potentially immune therapies." (PMID 41916083, 2026). "In an attempt to overcome this gap, our study aims to further clarify morphological differences between healthy melanocytes and NRAS‐mutant melanoma." (PMID 41486569, 2026). "In melanoma cells with BRAF and NRAS mutations, HSPB8 plays an anti-tumor role by regulating processes such as autophagy." (PMID 41490177, 2026). "Melanoma exhibits a high proliferative capacity largely due to frequent driver mutations, such as BRAF and NRAS." (PMID 41596235, 2026). "Compared with other studies of melanoma, we found fewer mutations in classical driver genes such as BRAF, NRAS or NF1." (PMID 41708869, 2026). "Nevi most often harbored canonical MAPK-pathway mutations in BRAF and NRAS, as well as in GRIN2A, while melanomas, along with BRAF and NRAS, frequently carried additional driver alterations in ARID1A, ARID2, CDKN2A, and PTEN." (PMID 41516405, 2026). "The aggressive nature of NRAS‐mutant melanoma contributes to poor patient prognosis, highlighting the need for early diagnosis." (PMID 41486569, 2026). "The increased invasion and metastasis of melanoma cells are linked to mutations in BRAF, NRAS, and NF1 genes." (PMID 42193039, 2026). "A detailed analysis of signaling in MAPKi-resistant NRAS-mutant melanoma revealed a critical subnetwork involving S6K1/2 and PPARα, essential for lipid metabolism in cancer." (PMID 41596686, 2026). "Conversely, NRAS-mutant and NF1-mutant melanomas are more aggressive and linked to poorer prognosis, while triple wild-type cases generally respond less favorably to immunotherapy." (PMID 41465101, 2025). "The anthelminthic agent mebendazole combined with trametinib was also tested on NRAS mutant melanoma cells." (PMID 40862737, 2025).